CEP85L (centrosomal protein 85L)
Description:
Plays an essential role in neuronal cell migration.
Synonyms: C6orf204; NY-BR-15; bA57K17.2; LIS10
Tractability: PROTAC: ubiquitination databases record sites on it.
Gene: Protein-coding gene on chromosome 6 (118,460,772 to 118,710,075, reverse strand). Ensembl gene ENSG00000111860.
Subcellular location: Cytoplasm, cytoskeleton, microtubule organizing center, centrosome
Gene Ontology:
Biological process: neuron migration
Cellular component: pericentriolar material; centrosome
Genetic constraint (gnomAD): Loss-of-function variants: 32 observed, 61.78 expected, observed/expected ratio (o/e) 0.52, 90% interval 0.39 to 0.7. The upper end of that interval is the gene's LOEUF score, 0.7, which puts it in group 2 of 6, group 1 being the genes least tolerant of losing a copy. Missense variants: 693 observed, 696.51 expected, observed/expected ratio (o/e) 0.99, 90% interval 0.93 to 1.06. Synonymous variants: 232 observed, 252 expected, observed/expected ratio (o/e) 0.92, 90% interval 0.83 to 1.03.
Gene-disease validity (ClinGen):
ClinGen rates the evidence that CEP85L causes each of these diseases.
lissencephaly 10 (autosomal dominant): Definitive.
Homologues: Orthologues: chimpanzee CEP85L (97% identical), macaque CEP85L (96% identical), dog CEP85L (92% identical), rabbit CEP85L (91% identical), pig CEP85L (88% identical), mouse Cep85l (86% identical), rat Cep85l (84% identical), guinea pig CEP85L (75% identical), tropical clawed frog cep85l (52% identical), zebrafish cep85l (44% identical). Paralogues in human: CEP85 (32% identical).
Diseases named in the same sentence as CEP85L in open-access papers:
CEP85L is named in the same sentence as 19 diseases in open-access papers, as found by Europe PMC text mining. Sharing a sentence is not in itself a finding about the gene and the disease. The quoted sentences say what the papers report.
Lissencephaly (3 papers, 2021 to 2024). A spectrum of malformations of cortical development caused by insufficient neuronal migration that subsumes the terms agyria, pachygyria and subcortical band heterotopia. "In the same year, variants in the CEP85L gene were described in a small group of 13 patients with sporadic predominant posterior lissencephaly, outlining some common clinical features in addition to the cerebral malformation." (PMID 34440382, 2021). "Variants in CEP85L, encoding a protein involved in the regulation of neuronal migration, have been recently described as causative of lissencephaly with a posterior-prevalent involvement of the cerebral cortex and an autosomal dominant pattern of inheritance." (PMID 34440382, 2021). "Recently, the CEP85L gene has been identified as involved in microtubule organization, and it has been indicated as a cause of predominantly posterior-expressed lissencephaly." (PMID 34440382, 2021). "Centrosomal protein 85 like (CEP85L) has broad tissue expression and has been linked to cancer and lissencephaly." (PMID 39567769, 2024). "Interestingly, as seen in Case 1, a posterior predominant gradient has been observed in lissencephaly patients with pathogenic LIS1 and CEP85L variants." (PMID 38194050, 2024). "Further data could be useful in order to better define CEP85L-related lissencephaly, and could derive from the re-analysis of the WES data of patients with radiological features of posterior lissencephaly and no molecular anomaly identified in other genetic loci." (PMID 34440382, 2021). "The present case report indicates the clinical variability associated with CEP85L variants that are not invariantly associated with severe phenotypes and poor outcome, and underscores the importance of including this gene in diagnostic panels for lissencephaly." (PMID 34440382, 2021). "In our patient, the regions of altered gyrification also present with a double-cortex appearance, a combination that has never been reported before in CEP85L-related lissencephaly." (PMID 34440382, 2021). "Unlike other conditions in which lissencephaly is present, such as LIS1-related cases, the neurological and intellectual outcome associated with CEP85L variants is widely variable, and patients may even show a normal or a slightly delayed development." (PMID 34440382, 2021).
angiosarcoma (2 papers, 2013 to 2019). A malignant tumor arising from the endothelial cells of the blood vessels. "Notably, some of these fusions (e.g. CEP85L/ROS1 in angiosarcoma) represent the first for that cancer type and thus provide important new biological insight." (PMID 23637631, 2013).
gastric cancer (1 paper, 2020). A primary or metastatic malignant neoplasm involving the stomach. "In addition, circ-CEP85L hindered the malignant phenotype of gastric cancer by absorbing miR-942-5p to increase NFKBIA expression." (PMID 33292255, 2020).
myeloproliferative neoplasm (1 paper, 2013). A clonal hematopoietic stem cell disorder, characterized by proliferation in the bone marrow of one or more of the myeloid (i.e., granulocytic, erythroid, megakaryocytic, and mast cell) lineages. "CEP85L was recently discovered to be the 5′ partner of a rearrangement involving PDGFRB in a patient with precursor T-ALL and an associated myeloproliferative neoplasm." (PMID 23637631, 2013).
Pachygyria (1 paper, 2024). Pachygyria is a malformation of cortical development with abnormally wide gyri with sulci 1,5-3 cm apart and abnormally thick cortex measuring more than 5 mm (radiological definition). "In contrast, both posterior predominant SBH and pachygyria have been independently observed in patients resulting from apparently germline CEP85L variants." (PMID 38194050, 2024).
cancer (3 papers, 2022 to 2025). A tumor composed of atypical neoplastic, often pleomorphic cells that invade other tissues. "Among these upregulated genes, Dennd4a, Nfil3, Hspa1b, Chac1, Ddit4, Mex3b, Lysmd3, and Zbtb10 are mainly involved in oxidative stress and inflammation response, whereas Plcxd2, Dusp1, Cep85l, and Dusp8 are generally considered as tumor‐suppressor genes by inhibiting proliferation of cancer cells." (PMID 40231790, 2025). "However, no studies demonstrated the role of ASXL3, TMOD2, and CEP85L in cancer." (PMID 35550610, 2022).
CNS tumors (1 paper, 2024). "Six different ROS1 fusion partners have already been described in pediatric CNS tumors (+/−7% of pediatric CNS tumors): GOPC, ARCN1, CHCHD3, ZCCHC8, TPR and CEP85L." (PMID 39409964, 2024).
CEP85L also shares sentences with these, for which no sentence is quoted: tumor (3 papers); breast carcinoma (2); anaplastic astrocytoma (1); Band Heterotopia (1); Cognitive impairment (1); colon cancer (1); heart failure (1); melanoma (1); myocardial infarction (1); Neurodevelopmental delay (1); pancreatic cancer (1); T-cell acute lymphoblastic leukemia (1).